INS (insulin)
Diseases named in the same sentence as INS in open-access papers (continued):
Sharing a sentence is not in itself a finding about the gene and the disease.
cancer (continued). "KEGG enrichment analysis identified crucial nodes in the signaling pathways associated with cancer development, including VEGFA, INS, IGF1R, and INSR." (PMID 38305809, 2024). "A range of systemic factors, including insulin-related signaling, however, can also induce carcinogenic signaling and shape cancer phenotypes." (PMID 38510653, 2024). "The cancer field has provided a large variety of experimental settings to confirm the major impact of the INSRα-A/B ratio on insulin responsivity and downstream cellular response." (PMID 37611907, 2024). "KEGG enrichment analysis showed that target genes of DE-tsRNAs chiefly participated in Insulin, ErbB, cancer, and FoxO signaling pathways." (PMID 38289488, 2024). "Long-term chronic inflammation and increased IGF-1/Insulin production can lead to cancer progression." (PMID 38339407, 2024). "Fasting insulin and insulin sensitivity improved in 13 patients (87%) after 3 months, revealing a highly positive outcome for adjuvant cancer treatment." (PMID 38166036, 2024). "Adiponectin exerts pleiotropic actions in various organs, i.e., it promotes insulin sensitivity, and apoptosis in cancer cells, primarily through its anti-inflammatory, anti-atherogenic, and insulin-sensitizing effects." (PMID 39125318, 2024). "During periods of fasting, there is a decrease in the levels of IGF-1 and insulin, which are growth factors that support the growth and survival of cancer cells." (PMID 39310400, 2024). "Metformin improves metabolic health and decreases circulating insulin and insulin-like growth factor 1 (IGF-1), both of which are known to promote cancer risk and progression." (PMID 38543182, 2024). "Antagonism of GRK6, a member of the G-coupled receptor kinase family associated with insulin secretion and T2D susceptibility, and PTK6, an oncogenic kinase studied in the context of cancer, led to the inhibition of T cell activation in the nM to uM range." (PMID 39302339, 2024). "Both in vitro and in vivo studies have highlighted the pivotal role of insulin and the insulin receptor in cancer biology." (PMID 39359726, 2024). "One proposed mechanism linking obesity and cancer involves elevated circulating insulin and insulin-like growth factor 1 (IGF-1) levels, which over-activate the IGF system." (PMID 39534224, 2024). "Furthermore, it has also been reported in non-diabetic and non-obese subjects that Hyperin itself is related to increased cancer deaths, and therefore the authors underline that a treatment to reduce circulating insulin levels could be an important therapeutic approach for the prevention of cancer." (PMID 39457728, 2024). "Microneedles (MNs) are a novel type of drug delivery system that has been widely used in cancer therapy, dermatological treatment, and insulin and vaccine delivery." (PMID 39554838, 2024). "Metformin, traditionally known as an insulin sensitizer, has recently been identified as an anti-cancer agent." (PMID 38543097, 2024). "The 6-phosphofructo-2-kinase/fructose-2,6-biphosphatase (PFKFB) family of proteins are bifunctional enzymes that are of clinical relevance because of their roles in regulating glycolysis in insulin sensitive tissues and cancer." (PMID 39763797, 2024). "Various experimental, epidemiological, and clinical evidence support the notion that insulin dysregulation plays a role in cancer progression." (PMID 38272982, 2024). "Combining aerobic and resistance exercises seems to improve insulin sensitivity, body composition, and overall quality of life in cancer survivors." (PMID 38339407, 2024). "Activation of IRS proteins occurs in cancer cells when insulin binds to the Insulin Receptor (IR), leading to a chain of intricate signaling cascades." (PMID 38272982, 2024). "The INSR pathway directly impacts cancer development in solid tumors, with insulin and IGF-II activation being prevalent in cancer cells, particularly in dedifferentiated/stem-like cells." (PMID 38731097, 2024).
cancer (continued). "This would mean that in the presence of insulin, the normoglycemic and hypoxic environment should allow cancer cells to proliferate." (PMID 39574543, 2024). "Compensatory insulin secretion worsens over time, contributing to further pancreatic function deterioration, cancer, and related disease progression." (PMID 38397883, 2024). "A correlation was found between elevated cancer onset and pioglitazone and insulin with its analogs, either intermediate or long-acting when combined with a fast-acting drug class in a study on the Taiwanese population." (PMID 39692821, 2024). "These abnormal conditions lead to the relative activation of epithelial cells to insulin, activating the insulin signalling pathway and promoting cancer cell proliferation and migration." (PMID 38116696, 2023). "The underlying mechanisms primarily involve insulin resistance, pro-inflammatory effect, and compensatory excess insulin production, which exhibit overlapping mechanisms with cancer." (PMID 37784113, 2023). "The aim of this study was to show that CAC scores differ significantly between insulin-sensitive- and -resistant cancer survivors." (PMID 37060010, 2023). "Elevated levels of IL-1β, IL-6, and TNF-α impair systemic insulin sensitivity and promote cancer development." (PMID 37175211, 2023). "Insulin signaling plays a role in cancer, including tumor initiation, progression, and response to treatment." (PMID 37679316, 2023). "Insulin has been shown to stimulate cancer cells, reduce apoptosis, and can increase carcinogenesis through IGF-1." (PMID 37069525, 2023). "The KEGG enrichment pathway mainly includes: axon guidance (bta04360), the phospholipase D signaling pathway (bta04072), insulin secretion (bta04911), choline metabolism in cancer (bta05231), etc." (PMID 36670743, 2023). "Insulin mediates cancer development not only through direct effects on cells but also through indirect effects on insulin-like growth factors (IGFs) and IGF-binding proteins (IGFBPs), increasing the bioactivity of IGF-1." (PMID 37686842, 2023). "In contrast, NASH-SFA genes were significantly enriched for pathways related to cancer, inflammatory response, and insulin signaling." (PMID 36765383, 2023). "Insulin is an anabolic hormone that acts through tyrosine-kinase membrane receptors, leading to mitogenic and anti-apoptotic effects, particularly in cancer cells that lose downregulation of the insulin receptor." (PMID 37364149, 2023). "In addition, higher consumption of fiber and whole grains, and low consumption of sugar-sweetened beverages may play an important role in regulating mechanisms associated with glucose control and insulin growth factor, which are related to a higher risk of cancer." (PMID 37764762, 2023). "MiR-212 and miR-132 are enriched in neurons but are also detected in other cells, such as immune cells, rat vascular smooth muscle cells, insulin-secreting β-cells, and several cancer types." (PMID 36769143, 2023). "A recent study using SRS imaging and deuterated water as a probe found that manipulating the level of L-Met together with insulin can alter de novo lipogenesis, the process of synthesizing new lipids, in cancer cells." (PMID 37065821, 2023). "Our data indicate that fasting enhances the ability of CBIs to lower cholesterol in cancer cells and that this effect is dependent on fasting-mediated reduction in insulin, IGF1 and leptin." (PMID 37907500, 2023). "Experimental studies suggest that insulin plays a role in cancer initiation and progression by increasing the likelihood of genetic alterations in normal cells and malignant cells." (PMID 37096432, 2023). "Non-cellulosic biological polymer-based pH-sensitive hydrogels have been widely researched for site-specific medication administration, cancer therapies, insulin delivery, and genetic material delivery." (PMID 37781530, 2023).
cancer (continued). "There is a huge body of evidence on the implications of the IGF/insulin signaling pathway in the progression and development of cancers, which indicates an important prognostic factor for patients." (PMID 37284192, 2023). "This leads to a decrease in insulin and insulin-like growth factors, which are known to be important for cancer cell proliferation." (PMID 37836444, 2023). "Local production of IGF-2 by epithelial and stromal cancer cells, along with an increased IR-A: IR-B ratio, supports the mitogenic response of cancer cells to insulin." (PMID 37834454, 2023). "Disruption of the insulin/IGF-1 signaling pathway is associated with several diseases (cardiovascular and neurodegenerative diseases, type II, cancer) and aging." (PMID 37895144, 2023). "Insulin signaling plays an important role in the development and progression of cancer since it is involved in proliferation and migration processes." (PMID 36975518, 2023). "Obesity also highly promotes the progression of various other cancers through mechanisms involving hormones, insulin and insulin-like growth factors, sex steroids, and obese inflammation." (PMID 37835451, 2023). "In summary, this trial is the first long-term tailored home-based exercise oncology trial to understand the long-term effects of exercise on fasting insulin levels, a surrogate indicator of cancer as well as an important indicator of metabolic health." (PMID 36864418, 2023). ",4,5,6,7,8,9In vitro studies have demonstrated that insulin signaling is mitogenic on cancer cells and can induce cell migration, providing possible mechanisms for carcinogenesis." (PMID 37250804, 2023). "The Kyoto Encyclopedia of Genes and Genomes (KEGG) pathway enrichment analysis showed that C. sativa was mainly involved in cancer-related pathways, lipids, and insulin signaling." (PMID 37754241, 2023). "Insulin signaling often plays a role in the regulation of cancer, including tumor initiation, progression, and response to treatment." (PMID 37679316, 2023). "During cancer cachexia, insulin and TGF‐β signalling converge in the fat body via Sog to hinder ECM secretion, which in turn affects muscle integrity." (PMID 38014610, 2023). "As the founding member of the protein tyrosine phosphatase (PTP) superfamily, PTP1B (encoded by PTPN1) has been reported to exert critical roles in many physiological and pathological processes, such as insulin signal transduction and cancer development." (PMID 36741874, 2023). "Preclinical and epidemiological studies suggest an important role of dysregulated metabolism in cancer development, in particular carcinogenic effects of sustained elevated insulin levels." (PMID 37250804, 2023). "Subsequent studies have found that sirtuins are involved in various physiological processes, including cell proliferation, apoptosis, cell cycle progression, and insulin signaling, and they have been extensively studied as cancer genes." (PMID 36975503, 2023). "Reduced circulating levels of insulin and bioavailability of IGF-I are linked to higher physical activity levels; they are mitogenic hormones that are associated with cancer formation." (PMID 38082394, 2023). "Carboxypeptidase A4 (CPA4) is a member of the metallo carboxypeptidase family which have been identified to be involved in cancer biology and insulin sensitivity." (PMID 36824368, 2023). "Together, our data suggest that TGF‐β and insulin signalling crosstalk is relevant in the context of cancer cachexia." (PMID 38014610, 2023). "The activating variations and their targeting by the activators lead to enhanced cellular proliferation, including the proliferation of cancer cell lines such as INS, which indicates a putative pro-oncogenic role for GCK." (PMID 37109475, 2023). "And, the abnormal accumulated glucose and insulin are instrumental in the transformation and progression of cancer." (PMID 37370018, 2023).
cancer (continued). "More research is needed to elucidate the complex interplays between cesarean delivery, insulin resistance, and the microbiome-immune-cancer axis throughout the life course." (PMID 37103933, 2023). "This activated insulin/IGF signaling in pancreatic ductal adenocarcinoma cells has been shown to regulate the cancer cells’ basal growth rate." (PMID 37623681, 2023). "The idea of insulin plus dexamethasone for cancer treatment came about after an accidental “mistake” in which a patient with advanced cancer misused a high-dose of insulin and his condition improved obviously." (PMID 37058027, 2023). "Kyoto Encyclopedia of Genes and Genomes (KEGG) pathway analysis revealed that the DEGTGs were enriched in the Rap1, Ras, MAPK, ERBB, PI3K-AKT, HIF-1, pathways in cancer, calcium, insulin, GnRH, and other signaling pathways." (PMID 37737707, 2023). "We found seven metabolism-related pathways, including insulin signaling pathway, carbon metabolism, thyroid hormone signaling pathway, biosynthesis of amino acids, central carbon metabolism in cancer, glycolysis/gluconeogenesis, and steroid biosynthesis." (PMID 37509438, 2023). "Several preclinical studies in mice have shown that dietary interventions leading to low insulin levels in the blood can enhance anticancer therapy and improve the outcomes of several cancers." (PMID 37679316, 2023). "Our results showed that the majority of miRNAs were mapped to several pathways involved in different diseases such as cancers,T2D, AD, and insulin signaling pathways." (PMID 37342358, 2023). "A global reduction in GHR expression led to improved insulin sensitivity, a reduction in cancer and an extension of lifespan in mice." (PMID 37881503, 2023). "Metformin-induced activation of the AMPK pathway is able to reduce the tumor-promoting activity of insulin and inhibit mTOR, which is closely related to tumor cell proliferation, making metformin an intriguing molecule in cancer therapy." (PMID 37686769, 2023). "IGFs are produced by cancer cells or by tumor stroma and bind at least six binding proteins with variable affinity, while insulin is produced solely by pancreatic beta cells and circulates in the unbound form." (PMID 36672737, 2023). "Visceral adipose tissue is more lipolytically active, contributing to the increase in free fatty acids and thus resulting in insulin resistance and to a more pro-cancer secretome than subcutaneous adipose tissue." (PMID 37686769, 2023). "Metformin, an insulin-sensitizing drug, displays anti-tumor effects in cancer patients, including EC, but the mechanism of action is still not completely understood." (PMID 37313172, 2023). "Physical inactivity, sedentary behavior, and obesity are probably related to cancer incidence via biological pathways, including insulin sensitivity, sex steroids, metabolic hormones, and chronic inflammation." (PMID 36834334, 2023). "The results showed that the pathways significantly enriched (p < 0.05) in GY-RG compared with those in GY-CG were choline metabolism in cancer, retrograde endocannabinoid signaling, insulin resistance, and linoleic acid metabolism." (PMID 37445854, 2023). "Goblet cells’ DEGs are enriched in pathways like insulin and ribosome signaling, and central carbon metabolism and proteoglycans in cancer, based on the KEGG database." (PMID 37880448, 2023). "The insulin signaling,endocytosis, and cancer-related pathways that were found prominentin both omics were also significantly enriched in the integrativeanalysis." (PMID 37581432, 2023). "Studies of some common cancers, such as breast and pancreatic cancers, have shown that hyperinsulinemia enhances tumor development in both humans and mice, while reduced insulin levels reduce tumor development." (PMID 37679316, 2023). "A low-CHO diet is used in order to starve cancer cells while also normalizing plasma insulin levels." (PMID 37686842, 2023).
cancer (continued). "Pathway enrichment analysis of DNAm probes associated with suicidal ideation also identified numerous KEGG terms, including AMPK signaling, insulin signaling, mTOR signaling, and numerous cancers (i.e., gastric, pancreatic, breast, and prostate)." (PMID 37398583, 2023). "In S-III, GO enrichment showed that genes were involved in the pathway of cancer progression, such as osteoclast differentiation (GO:0030316), insulin secretion (GO:0030073), and Ras protein signal transduction and cell growth (GO:0007265)." (PMID 38143770, 2023). "This review provides a comprehensive overview of the distinct functions attributed to p85α and p85β, highlighting their significance in various physiological processes, including insulin signaling, cancer development, and immune system regulation." (PMID 38317714, 2023). "Adipocytes in TME (via omentin) are capable of insulin-dependent glucose uptake—which results in local glucose reduction required by OC cancer cells (as well as other types of cancer cells) for cellular metabolism." (PMID 37568613, 2023). "It is, however, the consequence of two very different disease processes, type 1 (insulin‐dependent) and type 2 (non‐insulin‐dependent), (and several much rarer types), with different metabolic and hormonal characteristics and treatments that might affect cancer risk." (PMID 37190903, 2023). "In MCF-7, ZR75 and 4T1 BC cells, as well as in patient-derived Cancer-Associated Fibroblasts, the pharmacological inhibition of RAGE as well as its genetic depletion interfered with Insulin-induced activation of the oncogenic pathway IR/IRS1/AKT/CD1." (PMID 37461077, 2023). "These lipid metabolism states can contribute to the development of cancer by promoting inflammation, oxidative stress, insulin resistance and hormone imbalance and chronically activating growth factor signaling, which can all increase the risk of cancer." (PMID 37373069, 2023). "LCKD, 12-hour fasting and insulin administration prior to chemotherapy enhanced the effect of chemotherapeutics by making the membranes more permeable, depriving cancer cells of glucose and developing metabolic oxidative stress on the cells." (PMID 36829437, 2023). "Metformin is an anti-diabetic drug with potential anti-cancer effects, ranging from normalization of blood glucose and insulin levels, direct anti-proliferative effects on cancer cells to emerging immunomodulatory effects on anti-tumor immunity." (PMID 38116319, 2023). "The underlying principle of imaging is the preferentially increased glucose consumption by cancer cells, due to overexpression of glucose type 1 receptors that are insulin independent." (PMID 37854083, 2023). "These inflammatory cytokines have been shown to promote increases in circulating triglycerides, insulin resistance, growth, apoptosis, and tumor cell proliferation in many cancers." (PMID 36800961, 2023). "These include glycoprotective (sensitizing tissues to insulin), anti-inflammatory, antioxidant, anti-cancer, antiatherosclerotic, cardioprotective, and neuroprotective properties." (PMID 37511397, 2023). "Metformin was shown to have both systemic effects on glucose and insulin levels and to directly suppress cancer cell respiration via NADH oxidase." (PMID 38116319, 2023). "Several pieces of data indicate that phloroglucinol interferes with the insulin signaling pathway in human cancer cells." (PMID 37997977, 2023). "Insulin plays an important role in the development and progression of cancer because it is involved in the processes of cell growth and proliferation due to its stimulatory effects on DNA synthesis in various tissues." (PMID 36975518, 2023). "Adiponectin, one of the most extensively studied adipocyte-derived factors, exerts a plethora of beneficial effects through its insulin-sensitizing, anti-atherogenic, and anti-cancer properties." (PMID 36847916, 2023).